PRKD2 (protein kinase D2)
Description:
Serine/threonine-protein kinase that converts transient diacylglycerol (DAG) signals into prolonged physiological effects downstream of PKC, and is involved in the regulation of cell proliferation via MAPK1/3 (ERK1/2) signaling, oxidative stress-induced NF-kappa-B activation, inhibition of HDAC7 transcriptional repression, signaling downstream of T-cell antigen receptor (TCR) and cytokine production, and plays a role in Golgi membrane trafficking, angiogenesis, secretory granule release and cell adhesion. May potentiate mitogenesis induced by the neuropeptide bombesin by mediating an increase in the duration of MAPK1/3 (ERK1/2) signaling, which leads to accumulation of immediate-early gene products including FOS that stimulate cell cycle progression (By similarity). In response to oxidative stress, is phosphorylated at Tyr-438 and Tyr-717 by ABL1, which leads to the activation of PRKD2 without increasing its catalytic activity, and mediates activation of NF-kappa-B. In response to the activation of the gastrin receptor CCKBR, is phosphorylated at Ser-244 by CSNK1D and CSNK1E, translocates to the nucleus, phosphorylates HDAC7, leading to nuclear export of HDAC7 and inhibition of HDAC7 transcriptional repression of NR4A1/NUR77. Upon TCR stimulation, is activated independently of ZAP70, translocates from the cytoplasm to the nucleus and is required for interleukin-2 (IL2) promoter up-regulation. During adaptive immune responses, is required in peripheral T-lymphocytes for the production of the effector cytokines IL2 and IFNG after TCR engagement and for optimal induction of antibody responses to antigens (By similarity). In epithelial cells stimulated with lysophosphatidic acid (LPA), is activated through a PKC-dependent pathway and mediates LPA-stimulated interleukin-8 (IL8) secretion via a NF-kappa-B-dependent pathway. During TCR-induced T-cell activation, interacts with and is activated by the tyrosine kinase LCK, which results in the activation of the NFAT transcription factors. In the trans-Golgi network (TGN), regulates the fission of transport vesicles that are on their way to the plasma membrane and in polarized cells is involved in the transport of proteins from the TGN to the basolateral membrane. Plays an important role in endothelial cell proliferation and migration prior to angiogenesis, partly through modulation of the expression of KDR/VEGFR2 and FGFR1, two key growth factor receptors involved in angiogenesis. In secretory pathway, is required for the release of chromogranin-A (CHGA)-containing secretory granules from the TGN. Downstream of PRKCA, plays important roles in angiotensin-2-induced monocyte adhesion to endothelial cells. Plays a regulatory role in angiogenesis and tumor growth by phosphorylating a downstream mediator CIB1 isoform 2, resulting in vascular endothelial growth factor A (VEGFA) secretion.
Synonyms: PKD2; HSPC187; DKFZP586E0820; nPKC-D2
Tractability: Small molecule: a high-quality ligand is known; it belongs to a druggable protein family. Antibody: UniProt places it where antibodies can reach, with medium confidence; its Gene Ontology location is reachable by antibodies, with medium confidence. PROTAC: ubiquitination databases record sites on it; its protein half-life has been measured; a small molecule that binds it is known.
Target class: Kinase; Protein Kinase; Enzyme; CAMK protein kinase group; CAMK protein kinase PKD family
Safety:
Unwanted effects reported when the protein is acted on. In parentheses: how it was acted on, where the effect was seen, and who reports it.
cardiac arrhythmia (cardiovascular system; source: Lamore et al. (2017))
Gene: Protein-coding gene on chromosome 19 (46,674,275 to 46,717,127, reverse strand). Ensembl gene ENSG00000105287.
Subcellular location: Cytoplasm; Cell membrane; Nucleus; Golgi apparatus, trans-Golgi network
Subcellular location (Human Protein Atlas): Nucleoplasm; Cytosol
Pathways (Reactome):
Metabolism: Sphingolipid de novo biosynthesis
Gene Ontology:
Molecular function: protein binding; protein kinase activity; protein kinase C binding; protein serine kinase activity; protein serine/threonine kinase activity; diacylglycerol-dependent, calcium-independent serine/threonine kinase activity; ATP binding; diacylglycerol-dependent serine/threonine kinase activity
Biological process: cellular response to vascular endothelial growth factor stimulus; intracellular signal transduction; positive regulation of angiogenesis; positive regulation of blood vessel endothelial cell migration; positive regulation of cell adhesion; positive regulation of endothelial cell chemotaxis; positive regulation of endothelial cell migration; positive regulation of endothelial cell proliferation; positive regulation of fibroblast growth factor receptor signaling pathway; positive regulation of interleukin-8 production; positive regulation of transcription by RNA polymerase II; positive regulation of vascular endothelial growth factor receptor signaling pathway; protein phosphorylation; regulation of T cell apoptotic process; T cell receptor signaling pathway; vascular endothelial growth factor receptor signaling pathway; endothelial tube morphogenesis; phospholipase C-activating G protein-coupled receptor signaling pathway; positive regulation of DNA biosynthetic process; positive regulation of ERK1 and ERK2 cascade; positive regulation of interleukin-2 production; positive regulation of T cell receptor signaling pathway; sphingolipid biosynthetic process
Cellular component: cytoplasm; cytosol; nucleoplasm; nucleus; Golgi apparatus; plasma membrane
Genetic constraint (gnomAD): Loss-of-function variants: 23 observed, 85.54 expected, observed/expected ratio (o/e) 0.27, 90% interval 0.19 to 0.38. The upper end of that interval is the gene's LOEUF score, 0.38, which puts it in group 1 of 6, group 1 being the genes least tolerant of losing a copy. Missense variants: 818 observed, 1,196.3 expected, observed/expected ratio (o/e) 0.68, 90% interval 0.64 to 0.72. Synonymous variants: 509 observed, 515.36 expected, observed/expected ratio (o/e) 0.99, 90% interval 0.92 to 1.06.
Homologues: Orthologues: chimpanzee PRKD2 (99% identical), macaque PRKD2 (99% identical), pig PRKD2 (96% identical), dog PRKD2 (96% identical), mouse Prkd2 (95% identical), rat Prkd2 (95% identical), guinea pig PRKD2 (92% identical), rabbit PRKD2 (90% identical), Drosophila melanogaster PKD (50% identical), zebrafish prkd2 (49% identical), Caenorhabditis elegans dkf-2 (49% identical), Caenorhabditis elegans dkf-1 (35% identical). Paralogues in human: PRKD1 (69% identical), PRKD3 (65% identical).
Diseases named in the same sentence as PRKD2 in open-access papers:
PRKD2 is named in the same sentence as 34 diseases in open-access papers, as found by Europe PMC text mining. Sharing a sentence is not in itself a finding about the gene and the disease. The quoted sentences say what the papers report.
breast carcinoma (4 papers, 2018 to 2022). "PRKD2 affects drug resistance in various tumors such as breast cancer and leukemia by regulating tumor cell proliferation, apoptosis, metastasis, and invasion." (PMID 36059802, 2022). "To determine whether the expression of PKD family members is associated with prognosis in breast cancer, we first analyzed PRKD1, PRKD2 and PRKD3 mRNA levels by quantitative RT-PCR in a large series of 527 primary breast tumors with known clinical/pathological status and long-term outcome." (PMID 29796183, 2018). "Together, these results show that PRKD1, PRKD2 and PRKD3 are expressed in breast cancer and that PRKD1 mRNA expression is an independent prognostic factor in the entire BC population and in the TNBC subpopulation." (PMID 29796183, 2018).
myeloma (3 papers, 2018 to 2019).
chronic myeloid leukemia (2 papers, 2006 to 2022). "GABPA is necessary for chronic myeloid leukemia (CML) development through its regulation of protein kinase D2 (PRKD2)." (PMID 36035173, 2022). "Another gene down-regulated after Lhx2 expression is turned off is Prkd2 (Protein kinase D2), which has also been shown to be a substrate for the BCR-ABL fusion protein present in chronic myeloid leukemia cells." (PMID 16600034, 2006).
glioblastoma (2 papers, 2022 to 2025). The most malignant astrocytic tumor (WHO grade IV).
Obesity (2 papers, 2018 to 2021). Accumulation of substantial excess body fat. "The findings here thus pinpoint a novel function of PRKD2 in regulating β-cell insulin secretion in that PRKD2 deficiency primarily increases insulin secretion, and further induces obesity and IR." (PMID 29789568, 2018).
primary sclerosing cholangitis (2 papers, 2018 to 2024). "Additional common variant SNPs in kinases known to export Class IIA HDACs via phosphorylation, including SIK2 and PRKD2, are also associated with primary sclerosing cholangitis, suggesting aberrant regulation of HDAC7 nuclear export as a causative mechanism." (PMID 29664401, 2018). "In this work, colocalisation analyses nominate likely primary sclerosing cholangitis effector genes and biological mechanisms at five non-coding (UBASH3A, PRKD2, ETS2 and AP003774.1/CCDC88B) and one coding (SH2B3) primary sclerosing cholangitis loci." (PMID 39505854, 2024).
acute myeloid leukemia (1 paper, 2021). Acute myeloid leukemia (AML) is a group of neoplasms arising from precursor cells committed to the myeloid cell-line differentiation. "Moreover, PRKD2 expression has been correlated with key genes involved in Notch pathway in newly diagnosed acute myeloid leukemia (AML) patients and there is evidence that PRKD2 promotes proliferation and chemo-resistance of human AML cell lines through a mechanisms involving Notch activity." (PMID 33597201, 2021).
angiolipoma (1 paper, 2025). A lipoma with prominent vascularity. "In a study using whole-exome sequencing and targeted ultra-deep sequencing, the authors reported that 80% of angiolipoma cases harbored mutations in the protein kinase D2 (PRKD2) gene." (PMID 41281085, 2025).
Burkitt lymphoma (1 paper, 2010). A rare form of malignant mature B-cell non-Hodgkin lymphoma. "While a role for PRKD2 (Protein Kinase D2) in CLL is limited, low levels of PRKD2 expression and autophosphorylation have been reported to be a feature of a number of B-cell tumors including mantle cell and Burkitt's lymphoma, and ~50% of CLL/small lymphocytic lymphomas." (PMID 21307401, 2010).
cholangiocarcinoma (1 paper, 2024). A carcinoma that arises from the intrahepatic biliary tree (intrahepatic cholangiocarcinoma) or from the junction, or adjacent to the junction, of the right and left hepatic ducts (hilar cholangiocarcinoma). "Furthermore, Prkd2 has been identified as an inhibitory regulator of cholangiocarcinoma, a malignancy highly associated with PSC38." (PMID 39505854, 2024).
coronary heart disease (1 paper, 2021). "PRKD2 is significantly associated with coronary heart disease, but does not reach the genome-wide threshold." (PMID 33597201, 2021).
COVID-19 (1 paper, 2023). A disease caused by infection with severe acute respiratory syndrome coronavirus 2. "Analysis of the combined cohorts revealed elevated autoantibody responses against SPANXN4, STK25, ATF4, PRKD2, and CHMP3 proteins in COVID-19 patients." (PMID 37520825, 2023).
glioma (1 paper, 2020). A benign or malignant brain and spinal cord tumor that arises from glial cells (astrocytes, oligodendrocytes, ependymal cells).
Hyperinsulinemia (1 paper, 2018). An increased concentration of insulin in the blood. "Here we show that a protein kinase D2 (PRKD2) nonsense mutation (K410X) in two rhesus monkeys with extreme hyperinsulinemia along with IR and metabolic defects by using extreme phenotype sampling and deep sequencing analyses." (PMID 29789568, 2018). "Using integrative approaches, we identified a PRKD2 nonsense mutation in rhesus monkeys with hyperinsulinemia." (PMID 29789568, 2018). "In this study, through the combination of primate-based extreme phenotype sampling and mice model-based verification, we reveal that mutation of PRKD2 is involved in the pathogenesis of hyperinsulinemia which, in turn, results in IR and metabolic disorders." (PMID 29789568, 2018). "Although the human orthologous site of the monkey nonsense mutation is not polymorphic according to the 1000 Genomes Project, it is plausible that patients with loss-of-function mutations on PRKD2 gene should have similar phenotype of hyperinsulinism." (PMID 29789568, 2018). "Although our data support the hyperinsulinemia-causes-IR hypothesis, short-term PRKD2 inhibition or deficiency may have beneficial effect via enhancing glucose-stimulated insulin secretion." (PMID 29789568, 2018). "In this study, we have provided multiple lines of evidence that PRKD2 down-regulation is sufficient to enhance β-cell insulin secretion and subsequently induce hyperinsulinemia and systemic IR." (PMID 29789568, 2018). "Taking advantage of a PRKD2-KO mouse model, we demonstrate that PRKD2 deletion triggers hyperinsulinemia which precedes to IR and metabolic disorders in the PRKD2 ablation mice." (PMID 29789568, 2018). "Altogether, these results indicate that down-regulation of PRKD2 is involved in the pathogenesis of hyperinsulinemia which, in turn, results in IR and metabolic disorders." (PMID 29789568, 2018). "All together, these results strongly suggest that down-regulation of PRKD2 expression is sufficient to increase insulin level, and support a hyperinsulinemia-primary model that IR and obese progressively developed following hyperinsulinemia." (PMID 29789568, 2018). "The identification of PRKD2 nonsense mutation in hyperinsulinemic monkeys further motivated us to investigate the relationship between down-regulation of PRKD2 and hyperinsulinemia in PRKD2 gene knockout (PRKD2−/−) mouse model." (PMID 29789568, 2018). "First, using extreme phenotype sampling in conjunction with deep sequencing analysis, we have identified a nonsense mutation of PRKD2 (K410X) which is shared by both extreme hyperinsulinemia cases but not the other 57 rhesus monkeys of the same cohort." (PMID 29789568, 2018). "Taken together, these results jointly indicate that a deficiency in PRKD2 leads to hyperinsulinemia by regulating insulin secretion rather than altering insulin signaling." (PMID 29789568, 2018).
liver cancer (1 paper, 2023). An epithelial or non-epithelial malignant neoplasm that arises from the liver. "For instance, protein kinase D2 (PKD2) is implicated in the angiogenesis, metastasis, and invasion of various malignant tumors (e.g. liver cancer, lung cancer) after being activated." (PMID 38102722, 2023).
pancreatic tumor (1 paper, 2021). "We demonstrate that Protein Kinase D2 function in B cells is essential for expression of IL-35 and promotes pancreatic tumor growth." (PMID 35046933, 2021).
Rett syndrome (1 paper, 2021). A severe neurodevelopmental disorder affecting the central nervous system. "Moreover, PRKD2 deletion was found in Rett syndrome (RTT), another neurodevelopmental disorder affecting the nervous, musculoskeletal, and gastroenteric systems." (PMID 33807058, 2021).
salivary gland tumours (1 paper, 2024). "The detection of a PRKD1 p.Glu710Asp hotspot mutation or the translocation of one of the PRKD1, PRKD2, or PRKD3 genes is now considered highly specific for the diagnosis of PAC, as these molecular alterations are rarely detected in other salivary gland tumours." (PMID 38201647, 2024).
tumor (11 papers, 2020 to 2025). "PRKD2, a member of the serine-threonine kinase family, is crucial for the survival, proliferation, migration, and angiogenesis of tumor cells." (PMID 41378132, 2025). "For instance, HSP90 promoted tumor angiogenesis and growth by binding to and stabilizing protein kinase D2 and macrophage migration inhibitory factor." (PMID 39433507, 2024). "Regarding CRC, CIB1 induces tumor progression by promoting higher levels of vascular endothelial growth factor (VEGF) via Protein kinase D2 (PKD2) and thus is directly involved in angiogenesis." (PMID 34794407, 2021). "Regarding B cells, examination of the tumor immune infiltrate in both PKDi and Prkd2-S707A/S711A tumors by flow cytometry revealed that the frequency of infiltrating B cells was significantly decreased." (PMID 35046933, 2021). "In a xenograft experiment, PRKD2 silencing significantly delayed tumor growth of U87 cells." (PMID 32764572, 2020). "Thus, genetic variants that reduce PRKD2 expression may impair monocyte migration, subsequent tissue repair and regeneration, contributing to the PSC phenotype and subsequent neoplasia." (PMID 39505854, 2024). "Studies indicate that B cell receptor activation regulates B cell-derived IL-35 expression through downstream protein kinase D2 (PDK2), suppressing the immune capacity of anti-tumor T cells and fostering PC development." (PMID 38634049, 2024). "We also observed that activated Prkd2-S707A/S711A CD4+ and CD8+ T cells have significantly reduced IFNγ production ex vivo suggesting that T cell PKD function also plays a significant role in tumor growth." (PMID 35046933, 2021).
cancer (8 papers, 2018 to 2025). A tumor composed of atypical neoplastic, often pleomorphic cells that invade other tissues. "To parse apart the effects of immune PKD function from cancer-cell autonomous PKD function in PDAC, we orthotopically injected KPC4662 cells into Prkd2-S707A/S711A mice." (PMID 35046933, 2021). "Protein kinase D2 (PKD2) has been reported to be related with progression and invasion in various cancers." (PMID 30718593, 2019).
infection (1 paper, 2024). The state of being infected such as from the introduction of a foreign agent such as serum, vaccine, antigenic substance or organism. "We found that both mRNA and protein levels of PKD1(Prkd1), PKD2 (Prkd2), and PKD3 (Prkd3) were increased after HCoV-229E or HCoV-OC43 infection." (PMID 39540754, 2024).
metabolic disease (1 paper, 2018). A congenital disorder (due to inherited enzyme abnormality) or acquired (due to failure of a metabolically important organ) disorder resulting from an abnormal metabolic process. "The findings not only uncover a novel function of PRKD2 in regulating insulin secretion but also reveal a potential therapeutic target for metabolic diseases." (PMID 29789568, 2018).
PRKD2 also shares sentences with these, for which no sentence is quoted: cardiac hypertrophy (2 papers); hepatocellular carcinoma (2); breast tumors (1); congenital neutropenia (1); hypertrophic cardiomyopathy (1); leukemia (1); lung carcinoma (1); multiple myeloma (1); Pancreatic Cancer (1); sarcoma (1); thyroid tumor (1); triple-negative breast carcinoma (1).